ZRANB1 (zinc finger RANBP2-type containing 1)
Description:
Ubiquitin thioesterase, which specifically hydrolyzes 'Lys-29'-linked and 'Lys-33'-linked diubiquitin. Also cleaves 'Lys-63'-linked chains, but with 40-fold less efficiency compared to 'Lys-29'-linked ones. Positive regulator of the Wnt signaling pathway that deubiquitinates APC protein, a negative regulator of Wnt-mediated transcription. Acts as a regulator of autophagy by mediating deubiquitination of PIK3C3/VPS34, thereby promoting autophagosome maturation. Plays a role in the regulation of cell morphology and cytoskeletal organization. Required in the stress fiber dynamics and cell migration.
Synonyms: TRABID
Tractability: PROTAC: ubiquitination databases record sites on it.
Gene: Protein-coding gene on chromosome 10 (124,942,123 to 124,988,189, forward strand). Ensembl gene ENSG00000019995.
Subcellular location: Cytoplasm; Nucleus
Subcellular location (Human Protein Atlas): Nucleoplasm; Cytosol
Pathways (Reactome):
Metabolism of proteins: Ovarian tumor domain proteases
Signal Transduction: Degradation of beta-catenin by the destruction complex
Gene Ontology:
Molecular function: cysteine-type deubiquitinase activity; deubiquitinase activity; K63-linked polyubiquitin modification-dependent protein binding; polyubiquitin modification-dependent protein binding; protein binding; catalytic activity
Biological process: positive regulation of Wnt signaling pathway; protein deubiquitination; protein deubiquitination involved in ubiquitin-dependent protein catabolic process; protein K29-linked deubiquitination; protein K33-linked deubiquitination; protein K63-linked deubiquitination; positive regulation of canonical Wnt signaling pathway
Cellular component: cytoplasm; cytosol; nucleoplasm; nucleus
Genetic constraint (gnomAD): Loss-of-function variants: 16 observed, 84.16 expected, observed/expected ratio (o/e) 0.19, 90% interval 0.13 to 0.29. The upper end of that interval is the gene's LOEUF score, 0.29, which puts it in group 1 of 6, group 1 being the genes least tolerant of losing a copy. Missense variants: 570 observed, 902.85 expected, observed/expected ratio (o/e) 0.63, 90% interval 0.59 to 0.68. Synonymous variants: 290 observed, 307.59 expected, observed/expected ratio (o/e) 0.94, 90% interval 0.86 to 1.04.
Homologues: Orthologues: macaque ZRANB1 (100% identical), chimpanzee ZRANB1 (99% identical), mouse Zranb1 (99% identical), pig ZRANB1 (99% identical), rat Zranb1 (99% identical), dog ZRANB1 (99% identical), guinea pig ZRANB1 (99% identical), rabbit ZRANB1 (94% identical), tropical clawed frog zranb1 (90% identical), zebrafish zranb1b (80% identical), zebrafish zranb1a (75% identical), Drosophila melanogaster trbd (47% identical).
Diseases named in the same sentence as ZRANB1 in open-access papers:
ZRANB1 is named in the same sentence as 20 diseases in open-access papers, as found by Europe PMC text mining. Sharing a sentence is not in itself a finding about the gene and the disease. The quoted sentences say what the papers report.
hepatocellular carcinoma (5 papers, 2021 to 2023). A malignant tumor that arises from hepatocytes. "Suppression of expression level of ZRANB1 has been found to inhibit the growth and metastasis of hepatocellular carcinoma both in vitro and in vivo." (PMID 37679400, 2023).
breast carcinoma (4 papers, 2020 to 2025). "In breast cancer (BC), OTUD5, YOD1, OTUD6A, OTUD7B, ZRANB1, and TNFAIP3 were characterized as carcinogenic drivers." (PMID 40469292, 2025). "In breast cancer, for instance, OTUB1, YOD1, OTUD5, OTULIN, TNFAIP3, and ZRANB1 drove chemoresistance, whereas OTUD1 and OTUD3 were sensitized to chemotherapy." (PMID 40469292, 2025). "Based on the result of a previous study, we found that binding of zinc finger RANBP2-type containing 1 (ZRANB1) to EZH2 led to EZH2 deubiquitination, thereby stabilizing EZH2 protein expression in breast cancer." (PMID 33109776, 2020).
ovarian tumor (3 papers, 2023 to 2024). "The TRAF-binding domain-containing protein (TRABID)/ZRANB1 is an ovarian tumor (OTU) family DUB that cleaves K29, K33, and to a lesser extent K63 linkages." (PMID 38517379, 2024).
liver cancer (2 papers, 2022 to 2024). An epithelial or non-epithelial malignant neoplasm that arises from the liver. "However, another study reported that the deletion or downregulation of ZRANB1 was closely associated with the recurrence, metastasis, tumor volume, and disease stage of liver cancer significantly increased." (PMID 35875077, 2022). "Mechanistically, ZRANB1 stabilizes and binds SP1 through deubiquitination, which promotes liver cancer progression." (PMID 35875077, 2022).
cardiac hypertrophy (1 paper, 2025). "In the human cardiac hypertrophy dataset, GSE89714, OTUD7B and ZRANB1 was identified as the downregulated members of the OTU family." (PMID 40158182, 2025).
glaucoma (1 paper, 2018). Increased pressure in the eyeball due to obstruction of the outflow of aqueous humor. "Moreover, ZRANB1 knockdown reduced glaucoma-induced RGC apoptosis." (PMID 29748605, 2018).
glioma (1 paper, 2023). A benign or malignant brain and spinal cord tumor that arises from glial cells (astrocytes, oligodendrocytes, ependymal cells). "Tight regulation of ZRANB1 expression is critical in glioma." (PMID 37892185, 2023). "While the role of ZRANB1 (zinc finger RANBP2-type containing 1, TRABID) in glioma is still unclear, it is likely multifactorial in nature." (PMID 37892185, 2023).
Obesity (1 paper, 2024). Accumulation of substantial excess body fat. "Obesity, PIK3CG/PI3Kγ (phosphatidylinositol-4,5-bisphosphate 3-kinase catalytic subunit gamma) ablation, ZRANB1 (zinc finger RANBP2-type containing 1), and ADORA2A-AS1 (ADORA2A antisense RNA 1) all contribute to HCC development." (PMID 39463763, 2024).
renal carcinoma (1 paper, 2024). A carcinoma arising from the epithelium of the renal parenchyma or the renal pelvis. "Loss of zinc finger RANBP2-type containing 1 (ZRANB1), an E3 ubiquitin ligase responsible for SLC7A11 protein degradation, renders renal cancer cells resistant to ferroptosis." (PMID 39624080, 2024).
tumor (8 papers, 2020 to 2026). "ZRANB1 inhibition facilitated anti-tumor immune surveillance and was sensitive to anti-PD-1 therapy." (PMID 40469292, 2025). "However, in solid tumors, lower ZRANB1 levels coincide with epigenetic regulation that promotes interferon and inflammatory immune cell responses in the tumor microenvironment." (PMID 37892185, 2023). "In contrast, TRABID (ZRANB1) expression is downregulated in HCC tumor tissues." (PMID 35884607, 2022). "Reduced expression of ZRANB1, a favorable factor, in HCC tissues and cell lines, facilitated tumor recurrence and metastasis." (PMID 40469292, 2025). "Expression of ZRANB1 and USP54 was decreased in the GBM group compared to the AS and non-tumor groups." (PMID 37892185, 2023). "Based on molecular mechanism related assays, we concluded that FAM83C-AS1 binding to ZRANB1 promoted EZH2 deubiquitination and thereby inhibited EZH2 downregulation, which led to the enhanced protein stability of EZH2 in CRC tumor cells." (PMID 33109776, 2020).
cancer (7 papers, 2012 to 2024). A tumor composed of atypical neoplastic, often pleomorphic cells that invade other tissues. "Moreover, by comparing the 13 survival-related gene lists, seven genes (SLK, API5, BTBD2, PTAR1, VPS37A, EIF2B1, and ZRANB1) were found to be associated with prognosis in a variety of cancers." (PMID 32300588, 2020). "Moreover, ZRANB1, a downregulated circRNA, has been found to be closely associated with cancer." (PMID 37679400, 2023).
ZRANB1 also shares sentences with these, for which no sentence is quoted: prostate carcinoma (3 papers); Autoimmunity (1); colon carcinoma (1); colorectal cancer (1); melanoma (1); prostate tumor (1); retinal degeneration (1); steatosis (1); thyroid cancer (1).